KDM6A (lysine demethylase 6A)
Diseases named in the same sentence as KDM6A in open-access papers (continued):
Sharing a sentence is not in itself a finding about the gene and the disease.
diabetes (6 papers, 2013 to 2023). "At this point in time, we observed upregulation of tubule cell Kdm6a levels, like that previously observed in the glomeruli, podocytes, mesangial cells or tubule cells of mice and humans with diabetes or focal segmental glomerulosclerosis." (PMID 37655466, 2023). "Although hsa-miR-199b-3p was proven to relieve diabetes-induced kidney injury by inhibiting KDM6A expression, its upregulation was observed in HG-induced HK2 cells and the kidney tissues of STZ-induced mice." (PMID 34257820, 2021). "First, podocyte‐specific knockout of KDM6A in mice substantially protects against diabetes‐induced proteinuria and kidney injury." (PMID 30948420, 2019). "Furthermore, podocytes isolated from KDM6A‐KO mice with diabetes retained normal morphological characteristics and exhibited normal levels of nephrin and WT‐1 expression." (PMID 30948420, 2019). "Based on these results, we conclude that targeting KDM6A in podocytes could attenuate diabetes‐induced kidney injury." (PMID 30948420, 2019). "Importantly, inactivation or knockout of either KDM6A or KLF10 in mice significantly suppresses diabetes‐induced proteinuria and kidney injury." (PMID 30948420, 2019). "This same epigenetic mark can be erased by lysine-specific demethylase 6 (KDM6)A and KDM6B, and we previously reported that inhibition of KDM6 demethylases attenuated glomerular disease caused by diabetes, adriamycin nephrotoxicity or renal mass ablation, a finding substantiated elsewhere." (PMID 37655466, 2023). "In our current work, we identified that the inhibitor of histone lysine demethylase KDM6A, GSK-J4, was capable of ameliorating cardiomyocyte injury induced by lipotoxicity under diabetes." (PMID 35722096, 2022). "Inactivation of KDM6A and KLF10 in mice can significantly protect against diabetes‐induced proteinuria and kidney injury." (PMID 30948420, 2019).
esophageal squamous cell carcinoma (6 papers, 2016 to 2025). Esophageal squamous cell carcinoma (ESCC) is a type of esophageal carcinoma (EC) that can affect any part of the esophagus, but is usually located in the upper or middle third. "Moreover, KDM6A H101D & P110S, N1156T and D1216N mutations identified in esophageal squamous cell carcinoma (ESCC) patients showed the increased interaction with SND1 and enhanced resistance to genotoxin." (PMID 38850159, 2024).
meningioma (6 papers, 2020 to 2025). A generally slow growing tumor attached to the dura mater. "Novel somatic driver events identified in these meningiomas were chromatin remodeling and mutations in epigenetic regulators lysine demethylase 6A (KDM6A), chromodomain helicase DNA binding protein 2 (CHD2), and tumor suppressor phosphatase and tensin homolog (PTEN)." (PMID 39726707, 2024). "In addition, certain meningiomas harbor mutations in genes such as KDM5C, KDM6A, SMARCB1, and SMARCE1, which encode proteins involved in transcriptional chromatin remodeling (SMARCB1, SMARCE1) or histone demethylation (KDM5C, KDM6A)." (PMID 40787520, 2025). "In addition, nearly 10% of non-NF2 meningiomas harbor loss of function mutations of KDM5C and KDM6A, encoding histone lysine-specific demethylases, resulting in alterations in histone function and epigenetic regulation in meningiomas." (PMID 33194703, 2020). "Similarly, KDM6A alterations occurred significantly more often in WHO grade 3 meningiomas (n = 15/176, 9%) versus 13/441 (2.9%, p = 0.0046) and 2/220 (0.9%, p = 0.0001) in WHO grade 2 and 1 meningiomas, respectively." (PMID 33087175, 2020). "Importantly, we detected KDM6A alterations in 23/472 of all NF2-mutant (4.9%) versus 7/377 in NF2-wt meningiomas (1.9%) (p = 0.0234)." (PMID 33087175, 2020). "Furthermore, we found that the tumor suppressor gene and chromatin regulator KDM6A, which has been identified at low frequency in prior studies with smaller cohorts of meningioma, is more frequently altered in NF2-mutant high-grade meningiomas than previously noted." (PMID 33087175, 2020). "We also observed an enrichment in alterations in CDKN2A/B, KDM6A, ARID1A, PTEN, FBXW7, and SUFU in comparison with NF2-wt meningiomas." (PMID 33087175, 2020). "Taking into account that KDM6A, which is located on chromosome X and escapes X-inactivation, acts antagonistically to PRC2 and promotes H3K27 demethylation, our findings may partly explain the upregulated PRC2 activity in the NF2-mutant group of meningiomas after inactivation of KDM6A." (PMID 33087175, 2020).
multiple sclerosis (6 papers, 2020 to 2023). A progressive autoimmune disorder affecting the central nervous system resulting in demyelination. "Since Kdm6a/Utx expression in CD4+ T cells promotes disease in EAE, escape from XCI and overexpression of Kdm6a in females is consistent with the increased susceptibility of women to multiple sclerosis." (PMID 33498655, 2021). "Indeed, KDM6A was shown to be the most sexually dimorphic gene in CD4+ T cells from patients with multiple sclerosis and deletion of Kdm6a in mice was protective in experimental autoimmune encephalitis." (PMID 35966636, 2022). "Upon knockout of Kdm6a in a classic mouse model of multiple sclerosis (CD4+ T cell–mediated experimental autoimmune encephalomyelitis), reduced inflammation and a reduction of spinal cord damage to neuronal axons were observed compared with wild-type counterparts." (PMID 33183347, 2020). "The role of Kdm6a in autoimmunity has been recently illustrated in experimental autoimmune encephalomyelitis (EAE), the mouse model of multiple sclerosis (MS)." (PMID 33498655, 2021).
non-small cell lung carcinoma (6 papers, 2021 to 2025). A group of at least three distinct histological types of lung cancer, including non-small cell squamous cell carcinoma, adenocarcinoma, and large cell carcinoma. "On the other hand, KDM2B-mediated demethylation of H3K4me3, along with KDM6A-mediated demethylation of H3K27me3, has been found to promote EZH2 expression and the subsequent progression of non-small cell lung cancer." (PMID 34266408, 2021).
hepatocellular carcinoma (5 papers, 2017 to 2025). A malignant tumor that arises from hepatocytes. "Future work should incorporate loss‐of‐function experiments, validation of results in diverse hepatoma cell lines, and in vivo models to confirm the universality and therapeutic potential of KDM6A modulation in the future." (PMID 41244070, 2025). "This expression pattern is in concert with many recent findings, including an unbiased genetic screen that identified KDM6A as an EMT-suppressor in hepatocellular carcinoma cells." (PMID 29029452, 2017). "In contrast, KDM5C and KDM6A have been shown to exhibit tumor-suppressive effects (e.g., metabolic repression and inhibition of cell proliferation) in intrahepatic cholangiocarcinoma and hepatocellular carcinoma, respectively." (PMID 41301905, 2025).
liver cancer (5 papers, 2018 to 2025). An epithelial or non-epithelial malignant neoplasm that arises from the liver. "Because we found a higher expression of this gene in females’ liver and considering that males have an increased risk for hepatic cancer, KDM6A could possibly be involved in hepatic cancer protection in females." (PMID 29846646, 2018). "This complexity underscores the need for further understanding of KDM6A’s context‐dependent function in liver cancer." (PMID 41244070, 2025). "Nevertheless, compared to other HCC models, DEN is still a typical, preferred model that appears to recapitulate the occurrence and development of liver cancer for exploring the function of the KDM6A gene." (PMID 37846441, 2023). "Our current findings demonstrated that KDM6A not only promoted the occurrence and development of liver cancer, but also played an important role in targeted therapy for liver cancer." (PMID 37846441, 2023). "Genetic alterations as well as expression analyses of KDM6A were performed in patients with liver cancer." (PMID 34509979, 2022). "To gain further insights into the role of KDM6A in human liver cancer, we analysed KDM6A messenger RNA (mRNA) transcript in a cohort containing 76 HCCs and corresponding normal liver tissue." (PMID 34509979, 2022). "We found that KDM6A expression positively correlates with DEPTOR expression in liver cancer samples." (PMID 34509979, 2022). "Notably, HCC also harbors mutations in KMT2D, while KDM6A/UTX, an H3K27 demethylase within the COMPASS-like complex, has been functionally established as a potent tumor suppressor in pancreatic and liver cancers." (PMID 37261974, 2023). "Additionally, we used publicly available transcriptomic data (GEPIA portal) for the TCGA liver cancer data set and confirmed a strong positive correlation between KDM6A and DEPTOR (R=0.32, p=3.9e–10)." (PMID 34509979, 2022). "KDM6A expression was lost in 30% of patients with liver cancer." (PMID 34509979, 2022). "Additionally, we performed the same analyses also for a cohort of patients with cholangiocarcinoma (n=80), the second most common liver cancer, and found similar results as observed for HCCs, where low KDM6A protein levels are accompanied with low DEPTOR and high pS6RP levels." (PMID 34509979, 2022). "This correlation was not only confined to liver cancer, as using a pan-cancer data set (GEPIA portal) for KDM6A and DEPTOR mRNA expression also revealed a significant positive correlation of both transcripts (R=0.25, p=9.1e–141)." (PMID 34509979, 2022).
myeloid malignancies (5 papers, 2021 to 2025). "Both mutations were predicted to result in premature stop codons leading to the loss of Kdm6a, similar to mutations identified in myeloid malignancies." (PMID 40365824, 2025). "KDM6A contributes to myeloid malignancies in an enzymatic (H3K27me3 demethylation) and in a non-enzymatic manner." (PMID 34944554, 2021). "In summary, loss of KDM6A contributes to leukemogenesis and drug resistance in myeloid malignancies both dependent on and independent of its enzymatic activity." (PMID 34944554, 2021).
renal carcinoma (5 papers, 2012 to 2024). A carcinoma arising from the epithelium of the renal parenchyma or the renal pelvis. "In accordance with that, the H3K27 histone demethylase KDM6A is frequently mutated in renal carcinoma, KDM6A knockdown recapitulates the malignant phenotypes that L-2HG induced, and PRC2 knockdown did the opposite." (PMID 33842477, 2021). "Other gene mutations, such as FANCD2, FAT3, KDM6A, KDR, TET2, and TSC2, occurred twice in this MA cohort, which was quite different from other common types of renal carcinoma." (PMID 30111351, 2018). "In addition, a systematic sequencing approach in human renal cancers has identified UTX (KDM6A), Jarid1C (KDM5C) as genes mutated in renal carcinoma." (PMID 21924352, 2012).
Turner syndrome (5 papers, 2013 to 2025). Turner syndrome is a chromosomal disorder associated with the complete or partial absence of an X chromosome. "Increased X-linked gene expression due to impaired XCI due to KDM6A deficiency may contribute to phenotypes in a variety of tissues such as those observed in Kabuki and Turner syndromes in human." (PMID 39754175, 2025). "Of the escape genes, SHOX, STS, KDM5C, KDM6A, UBA1, and RPS4X were associated with Turner syndrome." (PMID 36457060, 2022). "The Kabuki phenotype, present in females who have one deleted KDM6A copy but absent in Turner syndrome females, may be due to partial silencing of the normal copy by X inactivation in Kabuki females, while Turner females would have one expressed copy in all cells." (PMID 23658530, 2013).
triple-negative breast carcinoma (4 papers, 2017 to 2023). An invasive breast carcinoma which is negative for expression of estrogen receptor (ER), progesterone receptor (PR), and human epidermal growth factor receptor 2 (HER2). "In a study on triple-negative breast cancer, recruitment of KDM6A was associated with tumor recurrence." (PMID 37474745, 2023). "The expression of the H3K27me3-demethylase KDM6A is reduced in stem-like subpopulations of mammary cell lines and stem cell-enriched triple-negative breast cancers, indicting the significance of H3K27me3 in cancer stem cell." (PMID 32410622, 2020). "Accordingly, we show that the expression of the H3K27me3-demethylase KDM6A is reduced in cells that have undergone EMT, stem-like subpopulations of mammary cell lines and stem cell-enriched triple-negative breast cancers." (PMID 29029452, 2017).
Alzheimer disease (3 papers, 2022 to 2024). A progressive, neurodegenerative disease characterized by loss of function and death of nerve cells in several areas of the brain leading to loss of cognitive function such as memory and language. "In a study assessing sex differences in vulnerability to Alzheimer’s disease, it was proposed that a second X chromosome in women confers resilience to the disease specifically through KDM6A." (PMID 36293143, 2022). "Therefore, the study indicated that KDM6A had a significant effect in the sex chromosome, helping to reduce mortality and prevent brain dysfunction in Alzheimer’s disease." (PMID 39256355, 2024). "KDM6A has been implicated in the observed female-bias in Alzheimer’s disease, although not all studies have identified KDM6A expression as a contributor." (PMID 38131901, 2023). "Finally, KDM6A expression in the human brain was higher in women than in men and in Alzheimer’s disease patients compared to controls." (PMID 36293143, 2022).
autoimmune encephalitis (3 papers, 2022 to 2025). Inflammation of the brain secondary to an immune response triggered by the body itself. "However, X genes also harbor immune-related functions that exacerbate phenotypes, as noted with Tlr7 in the brains of aging male mice and Kdm6a in lymphocytes of female mice in an experimental model of autoimmune encephalitis." (PMID 40043106, 2025).
brain cancer (3 papers, 2019 to 2024). A primary or metastatic malignant neoplasm affecting the brain. "KDM6A was significant in pediatric brain cancer and marginally significant in adenocarcinomas of the lung and stomach while KDM3A was marginally significant in stomach adenocarcinoma." (PMID 31294536, 2019). "Furthermore, pediatric brain cancers have been shown to contain somatic mutations in epigenetic regulator genes such as H3F3A, KDM6A, and MLL5133–135." (PMID 36909536, 2023).
esophageal cancer (3 papers, 2018 to 2025). A primary or metastatic malignant neoplasm involving the esophagus. "KDM6A, a histone demethylase, is involved in epigenetic regulation and has been reported to function as a tumor suppressor in several cancers, including bladder, breast, and esophageal cancers." (PMID 39833941, 2025).
gastric cancer (3 papers, 2021 to 2024). A primary or metastatic malignant neoplasm involving the stomach. "KDM6A is upregulated in gastric cancer and can regulate the expression of SALL4, thereby promoting the growth and metastasis of gastric cancer." (PMID 38840262, 2024).
hyperinsulinemic hypoglycemia (3 papers, 2022 to 2025). An inherited autosomal recessive syndrome characterized by the disorganized formation of new islets in the pancreas and congenital hyperinsulinism. "The mechanism of pathogenic variation in the KDM6A gene leading to hyperinsulinemic hypoglycemia is unclear." (PMID 38373926, 2024). "KS patients with KDM6A variants may be at higher risk for neonatal hyperinsulinemic hypoglycemia than those with KMT2D variants." (PMID 34232366, 2022).
kidney (3 papers, 2023 to 2025). "We observed a strong negative association between KDM6A‐mut signature score and other aberrations associated with bladder patients with PD‐L1 responders, and a strong positive correlation with CREBBP‐mut and EP300‐mut scores." (PMID 40693457, 2025).
myeloid leukemia (3 papers, 2020 to 2025). A clonal proliferation of myeloid cells and their precursors in the bone marrow, peripheral blood, and spleen. "KDM6A-null myeloid leukemia cells were more resistant to treatment with the chemotherapeutic agents cytarabine (AraC) and daunorubicin." (PMID 31201358, 2020).
neuroblastoma (3 papers, 2019 to 2022). Neuroblastoma (NB) is the most common solid, extracranial childhood tumor. "In summary, KDM6B is highly expressed in human neuroblastoma and its genomic locus is epigenetically modified for active gene transcription, which is distinct from its paralogs KDM6A and UTY." (PMID 34893606, 2021). "We then compared the RNA-seq transcript counts of KDM6B, KDM6A, and UTY in three large neuroblastoma cohorts and found that expression of KDM6B was significantly higher than that of KDM6A or UTY." (PMID 34893606, 2021). "KDM6A expression was not correlated with the differentiation state of neuroblastoma tumors and was not upregulated during neuronal differentiation of neuroblastoma cells induced by RA or HOXC9." (PMID 30631055, 2019). "Although both can remove H3K27me3, our data suggest that KDM6A is unlikely to have a significant role in regulation of neuroblastoma cell differentiation." (PMID 30631055, 2019). "To determine whether high expression of KDM6B in neuroblastoma is associated with active epigenetic modifications, we investigated the epigenetic landscapes at the genomic loci of KDM6B, KDM6A, and UTY in seven primary human neuroblastoma tissues sequenced at St." (PMID 34893606, 2021). "Also, KDM6B knockdown did not induce KDM6A in neuroblastoma cells." (PMID 30631055, 2019). "We have previously shown that KDM6B, but not KDM6A or UTY, is essential for neuroblastoma cell survival." (PMID 34893606, 2021). "We also found that levels of KDM6B expression, but not KDM6A or UTY, in neuroblastoma cell lines were among the highest, across 40 different cancer lineages." (PMID 34893606, 2021).
osteosarcoma (3 papers, 2017 to 2023). A usually aggressive malignant bone-forming mesenchymal neoplasm, predominantly affecting adolescents and young adults. "To determine whether KDM6A addiction is generated as an immediate consequence of HPV16 E7 expression or whether it is acquired after long-term E7 expression, we performed KDM6A depletion experiments in U2OS osteosarcoma cells with doxycycline-inducible HPV16 E7 expression." (PMID 28968467, 2017). "We also analyzed the mRNA expression of KDM6A and KDM6B in 20 matched osteosarcoma and peritumoral tissues; the results showed that compared with normal peritumoral tissue, OS tissue expressed higher levels of KDM6A and KDM6B." (PMID 30651137, 2019).
pancreatic adenocarcinoma (3 papers, 2019 to 2024). "Consistent with an increased transcriptional response to hypoxia in pancreatic adenocarcinomas bearing KDM6A inactivation, we showed that mutation or reduced KDM6A expression in SPNs is associated with increased expression of the HIF1α‐regulated protein GLUT1 at both primary and metastatic sites." (PMID 30306561, 2019). "KDM6A mutant pancreatic adenocarcinoma (PAAD) was sensitive to JQ1." (PMID 38566153, 2024).